U2 (U2 spliceosomal RNA )
Synonyms: LOC124904641
Gene: Small nuclear RNA gene on chromosome 1 (120,571,120 to 120,571,264, forward strand). Ensembl gene ENSG00000273694.
Gene Ontology:
Molecular function: pre-mRNA branch point binding
Biological process: mRNA branch site recognition
Cellular component: U2 snRNP
Homologues: Orthologues: dog U2 (54% identical), rabbit U2 (52% identical). Paralogues in human: RNU2-38P (54% identical), RNU2-28P (53% identical), RNU2-55P (52% identical), RNU2-2 (50% identical), RNU2-6P (50% identical), U2 (50% identical), RNU2-36P (49% identical), RNU2-53P (49% identical), U2 (49% identical), RNU2-13P (48% identical), RNU2-47P (48% identical), RNU2-10P (47% identical), and 65 more.